IGLC6 (immunoglobulin lambda constant 6)
Description:
Constant region of immunoglobulin light chains. Immunoglobulins, also known as antibodies, are membrane-bound or secreted glycoproteins produced by B lymphocytes. In the recognition phase of humoral immunity, the membrane-bound immunoglobulins serve as receptors which, upon binding of a specific antigen, trigger the clonal expansion and differentiation of B lymphocytes into immunoglobulins-secreting plasma cells. Secreted immunoglobulins mediate the effector phase of humoral immunity, which results in the elimination of bound antigens. The antigen binding site is formed by the variable domain of one heavy chain, together with that of its associated light chain. Thus, each immunoglobulin has two antigen binding sites with remarkable affinity for a particular antigen. The variable domains are assembled by a process called V-(D)-J rearrangement and can then be subjected to somatic hypermutations which, after exposure to antigen and selection, allow affinity maturation for a particular antigen.
Synonyms: IGLC
Gene: Gene (Ensembl biotype IG_C_pseudogene) on chromosome 22 (22,919,535 to 22,919,851, forward strand). Ensembl gene ENSG00000222037.
Subcellular location: Secreted; Cell membrane
Diseases named in the same sentence as IGLC6 in open-access papers:
IGLC6 is named in the same sentence as 1 disease in open-access papers, as found by Europe PMC text mining. Sharing a sentence is not in itself a finding about the gene and the disease. The quoted sentences say what the papers report.
tumor (1 paper, 2023). "Except for IGLC4, IGLC5, and IGLC7, 4 IGLC (IGLC1, IGLC2, IGLC3, and IGLC6) expressions were positively correlated with infiltration scores of 6 tumor-infiltrating immune cells (B cell, T cell CD4, T cell CD8, neutrophil, macrophage, and DC)." (PMID 37784026, 2023). "In RNAss database, tumor stemness was confirmed to be negatively correlated with the expressions of IGLC1 (r = -0.15, P = 0.01), IGLC2 (r = -0.16, P = 0.01), IGLC3 (r = -0.15, P = 0.01), and IGLC6 (r = -0.13, P = 0.03) respectively." (PMID 37784026, 2023).